SHBG (sex hormone binding globulin)
Diseases named in the same sentence as SHBG in open-access papers (continued):
Sharing a sentence is not in itself a finding about the gene and the disease.
diabetes (continued). "It has also been hypothesized that early menarche is a function of sex hormone exposure, such as higher levels of estradiol and lower sex-hormone-binding globulin concentrations, in women, which may affect glycaemic regulation and increase risk of diabetes." (PMID 31905226, 2020). "Although the mechanisms driving this relationship remain unclear, existing evidence suggests a causal role of SHBG in the development of diabetes." (PMID 32128321, 2019). "Lower SHBG levels are associated with a higher prevalence of diabetes and metabolic syndrome." (PMID 32128321, 2019). "In addition, a single nucleotide polymorphism related to an elevated plasma SHBG concentration reportedly correlates with a reduced risk of diabetes." (PMID 30046278, 2018). "Associations of SHBG, FT and TT with prediabetes and diabetes in 2654 male subjects." (PMID 27583401, 2016). "Both low SHBG and low TT levels were associated with increasing presence of prediabetes and diabetes, whereas only the association between serum SHBG and prediabetes and diabetes maintained statistically significant in fully adjusted model, especially in elderly prediabetic men." (PMID 27583401, 2016). "SHBG polymorphisms are predictive of type 2 diabetes mellitus riskin the Physicians Health Study." (PMID 25647406, 2015). "Genetic studies have defined a causal relationship between SHBG and type 2 diabetes mellitus." (PMID 29043159, 2013). "Further studies to delineate the underlying mechanism behind the association between SHBG and type 2 diabetes mellitus are advocated as they may provide a novel target for prevention and management of type 2 diabetes mellitus." (PMID 29043159, 2013). "After adjusting for age, family history of diabetes, smoking, physical activity, BMI, and FLI, SHBG levels were inversely associated with diabetes among women (odds ratio [OR] comparing the highest with the lowest quartiles, 0.13 [95% confidence interval {CI}, 0.02–0.96]), but not among men." (PMID 23066943, 2012). "In this well-characterized case–control study in a Japanese population, we identified SHBG levels in women and total and free testosterone levels in men to be inversely associated with diabetes after multivariable adjustment for FLI and fasting insulin as well as known risk factors for diabetes." (PMID 23066943, 2012). "Our findings suggest that SHBG in women and testosterone in men may be inversely associated with diabetes." (PMID 23066943, 2012). "Third, we did not ask women about the use of exogenous estrogen, which might have confounded the SHBG-diabetes association." (PMID 23066943, 2012). "A systematic review and meta-analysis showed that SHBG was inversely associated with incident and prevalent diabetes in both men and women after adjustment for known risk factors for type 2 diabetes and the inverse association was stronger in women than in men." (PMID 23066943, 2012). "SHBG binds to androgens and estrogens, thereby influencing their bioavailability with evidence from the present HCHS/SOL cohort demonstrating inverse associations of SHBG with diabetes and glycemic traits in postmenopausal women, although specific pathways remain unclear." (PMID 39743011, 2025). "Plasma estrogen induces SHBG production in the liver, which is significantly lower in postmenopausal women compared with premenopausal women; this decrease in SHBG levels is not only associated with IR but is also an independent risk factor for the development of diabetes." (PMID 36072812, 2022). "Moreover, SHBG levels were inversely correlated with glycated hemoglobin, suggesting that SHBG levels seem to be associated with alteration in glucose homeostasis, even before the development of diabetes." (PMID 36235799, 2022).
diabetes (continued). "Although the exact mechanisms by which SHBG influences the diabetes risk remain largely unclear, SHBG may contribute to the impairment of glucose metabolism through modulation of sex hormone bioavailability and direct activation of a specific receptor for SHBG." (PMID 23066943, 2012). "Subjects with lower serum ferritin concentrations (<50 ng/mL) had longer diabetes duration, lower AMMi, direct bilirubin, serum creatinine, triglycerides, SHBG, red blood cell parameters, and platelet count compared to subjects with normal ferritin levels." (PMID 41010909, 2025). "We constructed genetic scores for total testosterone, SHBG levels, and hypogonadism and find that men with higher testosterone genetic scores have lower odds of diabetes, hyperlipidemia, gout, and cardiac disorders." (PMID 40316537, 2025). "The distribution of diabetes between the two SHBG groups was not different (p=0.18), and there was a noticeable trend toward higher rates of diabetes among women with lower SHBG levels, suggesting a potential link worthy of further investigation." (PMID 40135042, 2025). "As the duration of diabetes increases, a declining ratio of testosterone to SHBG has been observed, which leads to a reduced availability of biologically active testosterone." (PMID 39682196, 2024). "A significant contributor to the reduction of T levels in individuals with diabetes is attributed to reduced sex hormone binding globulin." (PMID 39456785, 2024). "The poverty income ratio was inversely correlated with both testosterone and the T/E2 ratio, while the diabetes status showed positive correlations with both estradiol and SHBG." (PMID 39224565, 2024). "The present results enrich our understanding of the different roles of SHBG and androgen excess with the type and severity of hyperglycaemia during pregnancy as well as provide knowledge of the early steps of the diabetes cascade." (PMID 36484476, 2023). "A meta-analysis found that lower levels of sex hormone-binding globulin and greater levels of estradiol raise the likelihood of diabetes in women." (PMID 37794370, 2023). "More information is needed in the future to identify strategies to increase circulating SHBG concentrations and to better inform possible prevention strategies for diabetes in overweight/obese women." (PMID 36767197, 2023). "SHBG has emerged as a metabolic biomarker; low SHBG levels were reported to be predictive for type 2 diabetes mellitus (T2DM) in males and females, and an inflammatory mediator in the pathogenesis of metabolic disease." (PMID 37685811, 2023). "The presence or absence of arthritis was associated with age, sex, race, marriage, BMI, waist circumference, education, smoking status, estradiol, SHBG, hypertension, diabetes mellitus, and cardiovascular disease." (PMID 37935765, 2023). "The top five keywords clusters are “sex-hormone-binding globulin,” “luteinizing hormone,” “diabetes mellitus,” “quality of life,” and “metformin.”." (PMID 35968428, 2022). "Female patients with chronic inflammatory diseases, such as diabetes, presented low plasma SHBG levels." (PMID 35493382, 2022). "With modest test set performances (e.g., SHBG r = 0.18 and ACY-1 r = 0.25), it is perhaps surprising that such strong synergy is observed between EpiScores for proteins that associated with diabetes and the trends seen with measured proteins." (PMID 35023833, 2022). "In patients with diabetes and metabolic syndrome, plasmatic SHBG levels also show decreased levels compared with controls." (PMID 34335746, 2021). "In addition, it was found that the association between low levels of free testosterone and diabetes was abolished and that between low levels of total testosterone and diabetes was attenuated after adjusting for BMI (Body Mass Index) while in case of SHBG, the association was unaffected." (PMID 33047895, 2020). "Decreased SHBG levels are usually accompanied by abnormal metabolic status and predict the development of diabetes mellitus." (PMID 32326011, 2020).
diabetes (continued). "In regression analysis, age, BMI, waist circumference, hypertension, fasting insulin, testosterone, SHBG, FAI, and family history of diabetes were significant factors associated with glucose intolerance." (PMID 29707577, 2018). "Other studies have also shown that low testosterone and SHBG levels to also predict the development of MetS as well as diabetes and that elevated testosterone and SHBG led to increased insulin sensitivity and reduced risk of MetS." (PMID 30057912, 2018). "Levels of sex hormone-binding globulin (SHBG), as well as free testosterone, were not measured in the present study, which is of relevance since SHBG was shown to predict incident diabetes in men." (PMID 30127326, 2018). "Age, SHBG, FAI, FSH, LH, HbA1c, FPG, diabetes, systolic pressure and UA had strong association with ED." (PMID 28522875, 2017). "In covariance analysis, SHBG of prediabetes were found lower than that of normoglycemia but higher than that of diabetes (P <0.05)." (PMID 27583401, 2016). "After adjusting for age, smoking, neck and hip circumference, diabetes and hypertension, VAI was inversely associated with total testosterone, estradiol and SHBG (P < 0.01)." (PMID 26796865, 2016). "Further studies are needed to determine the potential role of low SHBG in the development of prediabetes and diabetes." (PMID 27583401, 2016). "SHBG levels are low in adults with T2DM, and many studies show that low levels predict diabetes risk." (PMID 26761949, 2016). "It is possible that dysglycaemia and BLLs work antagonistically on SHBG levels, resulting in only minor increases among subjects with diabetes." (PMID 27898110, 2016). "In linear regression, after adjusting for age, current smoking status, body mass index, systolic blood pressure, diabetes and blood cadmium level, TT (P for trend = 0.001) and SHBG (P for trend < 0.001) levels were still positively associated with BLLs in men." (PMID 27898110, 2016). "Low levels of testosterone and sex hormone-binding globulin have also been shown to be predictive factors for the development of both metabolic syndrome and diabetes in middle-aged men 39–50." (PMID 23668396, 2014). "This suggests that the interaction between diabetes, sex-hormone levels and prostate cancer is complex, with increased levels of sex hormone-binding globulin being a possible factor in the reduced incidence of prostate cancer." (PMID 23668396, 2014). "The potential influence of oestrogens in the progression of diabetes in rats is known and this is possibly enhanced by depletion of SHBG in female rats." (PMID 24499599, 2013). "There is a paucity of data on the relationship of SHBG with type 2 diabetes mellitus in subjects of African ancestry." (PMID 29043159, 2013). "In humans, recent investigations carried out in postmenopausal women reported an inverse relationship between serum concentrations of sex hormone binding globulin (SHBG) and the risk of clinical diabetes." (PMID 24499599, 2013). "First, we were unable to establish a temporal relationship between the exposure (i.e., testosterone and SHBG) and diabetes." (PMID 23066943, 2012). "Future studies should incorporate free testosterone and SHBG assessments, employ longitudinal designs to establish temporality, and evaluate the effect of interventions such as lifestyle modification, diabetes control, or TRT on erectile outcomes in Pakistani populations." (PMID 41170246, 2025). "TT, FT and SHBG were lower in obese men and men with diabetes compared to normal weight men and men without diabetes, correspondingly, while oestradiol was higher in obese men, with minimal difference according to diabetes status." (PMID 38234143, 2024). "Our study showed a decrease in SHBG together with cFT among the diabetes group." (PMID 38943183, 2024). "Whether SHBG could be a target therapy for reducing sex differences in diabetes needs larger and well-designed clinical studies." (PMID 38954350, 2024).
diabetes (continued). "Risk factors associated with low SHBG levels include elevated body mass index, diabetes, race (Hispanic, non-Hispanic black, or non-Hispanic white), chronic obstructive pulmonary disease, coronary heart disease, smoking and exposure to phthalates." (PMID 39026336, 2024). "Concomitant significant reduction in SHBG in the diabetes group (p < 0.001)." (PMID 38943183, 2024). "Men with diabetes had lower testosterone, SHBG, DHT and estradiol." (PMID 37639720, 2023). "Additionally, studies have shown that lower levels of sex-hormone binding globulin (SHBG) in women have been associated with central adiposity, diabetes, and CVD risk." (PMID 36712262, 2022). "Additionally, lower serum total testosterone and sex hormone binding globulin levels were found in patients living with diabetes." (PMID 35382807, 2022). "Stratified analyses indicated that the negative relationship of the total testosterone with all-cause death risk was independent of factors involving age, race, body mass index, diabetes, hypertension, C-reactive protein, creatinine, and sex hormone binding globulin." (PMID 36124237, 2022). "Thus, obesity (via decreased adiponectin), diabetes mellitus (via increased glucose), and inflammation can all alter SHBG levels." (PMID 33553985, 2021). "We considered, separately for men and women, potential mediating effects of the following variables: CRP, creatinine, vitamin D, calcium, ALP, IGF1, SHBG, testosterone, testosterone/SHBG, estradiol, phosphate, cystatin C, hypertension, diabetes, and hypercholesterolemia." (PMID 32964541, 2021). "Moreover, the relationship of SHBG with diabetes is bi-directional, as insulin inhibits hepatic SHBG production." (PMID 32128321, 2019). "Previous research has indicated that SHBG are negatively correlated with glycosylated hemoglobin in people without diabetes, which indicates that there may be a relationship between SHBG and glucose homeostasis changes before diabetes." (PMID 31752806, 2019). "A possible direct effect of SHBG on diabetes mellitus was suggested by a recent report." (PMID 30321217, 2018). "Furthermore, previous studies also suggested low SHBG as a predictor for cardio-metabolic morbidity, metabolic syndrome and type 2 diabetes mellitus." (PMID 29324787, 2018). "Recent data suggest that SHBG levels during pregnancy may contribute to and predict the development of adiposity, metabolic syndrome and diabetes as children grow older." (PMID 30321217, 2018). "We observed that the levels of HOMA-IR, fasting insulin, BMI, WC, TG, TC, FBG as well as the prevalence of hypertension and diabetes stepwise increased, while serum total T, E2, SHBG, FSH and LH level stepwise declined with the increasing TyG quartiles (all P for trend < 0.01)." (PMID 29158535, 2017). "After additional adjustments for diabetes and hypertension, for total T (Beta = −0.202), E2 (Beta = −0.052) and log-SHBG (Beta = −0.159), the association with VAI did not change (all P < 0.01)." (PMID 26796865, 2016). "Low serum SHBG was the most relevant factor for prediabetes and diabetes." (PMID 27583401, 2016). "Among various androgen values, low serum SHBG was the most relevant factor for prediabetes and diabetes, and whether it is an independent predictor for incident prediabetes in Chinese men needs further explorations." (PMID 27583401, 2016). "While the exact mechanism may be complex and involve more factors, the SHBG level, at least in part, explains the discrepant levels of total testosterone and free testosterone in men with prediabetes or diabetes." (PMID 24069277, 2013). "Since genetic studies are a powerful epidemiological tool, their findings may now help to more deeply address the complex and indubitably important role of circulating SHBG in the natural history of type 2 diabetes mellitus." (PMID 29043159, 2013).
diabetes (continued). "In T2D, the levels of SHBG were lower than in subjects without diabetes, but the association became insignificant after the adjustment for fasting glucose levels." (PMID 23781314, 2013). "The interaction for gender was significant for free testosterone (P-value = 0.008), although this might have been driven by the sex-difference in the SHBG-diabetes relation." (PMID 23066943, 2012). "Taken together, these findings support the role of SHBG in the development of diabetes." (PMID 23066943, 2012). "This suggests a sexual-dimorphism in the relation between free testosterone and diabetes; however, the effect measure modification might have been mainly driven by the SHBG-diabetes relation." (PMID 23066943, 2012). "Further adjustment for FLI slightly attenuated the association, but the strong inverse association observed in women remained (OR, 0.13 [95% CI, 0.02–0.96]) (Model 3), suggesting that the inverse association of SHBG with diabetes is independent of fatty liver." (PMID 23066943, 2012). "SHBG and PRSS2 might explain the beneficial association with IHD; testosterone, SHBG, CCL5, CNDP1, F11, LCN2, and THBS4 might explain the association with diabetes, which provides insights for drug development." (PMID 41882153, 2026). "Although some studies have suggested that SHBG levels might be related to other comorbidities such as metabolic syndrome, diabetes, and coronary heart disease (CHD), the mechanisms for these relationships are still largely unknown and a possible field for future investigation." (PMID 37568378, 2023). "In this prospective study, lifestyle interventions directed to obtain favorable changes in circulating levels of SHBG in men and women could not show to influence the risk of developing type 2 diabetes mellitus in the participants." (PMID 34335746, 2021). "We observed little evidence of association between SHBG and self-reported doctors-diagnosis of diabetes (field ID 2443, P = 0.368) or self-reported type-2 diabetes (field ID 20002, value code #1223, P = 0.454) in the MR-pheWAS, despite prior observational and genetic evidence of a protective effect." (PMID 32533189, 2020). "Increasing evidence suggests that high plasma estradiol and testosterone levels and low sex hormone-binding globulin levels may be associated with a higher risk of diabetes in women, independent of adiposity." (PMID 28605451, 2018). "Furthermore, there was a direct association between FAI levels and frequency of glucose intolerance (OR = 2.480, 95% CI 1.387–4.434), even after adjusting for age, BMI, waist circumference, hypertension, fasting insulin, testosterone, SHBG, and family history of diabetes." (PMID 29707577, 2018). "We aimed to study the association between endogenous insulin and SHBG-concentrations, and to estimate the differences in SHBG levels between subjects with T1D and T2D, and subjects without diabetes, respectively, in a population-based sample in South-western Sweden." (PMID 23781314, 2013). "The finding that prediabetes or diabetes is significantly associated with total testosterone but not free testosterone may be explained by a mechanism associated with SHBG." (PMID 24069277, 2013). "As fatty liver has been suggested to be a major determinant of SHBG levels, we examined whether the associations of SHBG and testosterone with diabetes were independent of fatty liver." (PMID 23066943, 2012). "This is thought to be due to decreased levels of serum sex hormone-binding globulin (SHBG) and increased levels of insulin in umbilical cord blood in pregnant women with diabetes, which interfere with testicular descent." (PMID 39439600, 2024). "This relationship remained constant even after the addition of other factors (age, sex, race, education level, marital status, BMI, alcohol status, smoking status, hypertension, diabetes, CVD, estradiol, SHBG, income to poverty ratio,)." (PMID 37935765, 2023).